ASCL1 (achaete-scute family bHLH transcription factor 1)
Diseases named in the same sentence as ASCL1 in open-access papers (continued):
Sharing a sentence is not in itself a finding about the gene and the disease.
glioma (continued). "ASCL1 knockdown caused large, statistically significant reductions in cell viability in XIII and XVII parental gliomas, whereas XIII-WT and XVII-WT exhibited smaller reductions." (PMID 32647372, 2020). "ASCL1 expression is maintained in both xenografts from human proneural GBM samples and GBM mouse models, and ASCL1 can induce cell cycle genes and oncogenes, thereby promoting glioma cell proliferation in some contexts." (PMID 33076453, 2020). "Together, these studies support the conclusion that ASCL1 levels in gliomas acts in a balance with both Wnt and Notch signaling pathways to regulate the GSC status of tumor cells in culture." (PMID 32573857, 2020). "Chromatin immunoprecipitation followed by deep sequencing (ChIP‐seq) has previously been performed for ASCL1 in glioma cell lines in culture, and a dual role for ASCL1 was proposed to either promote or attenuate tumorigenicity depending on context." (PMID 32573857, 2020). "Taken together, these findings demonstrate that a major role for ASCL1 in the Nf1;Tp53CKO glioma mouse model is to drive tumor cell proliferation." (PMID 32573857, 2020). "Increased H3K27me3 peaks at ASCL1 with reversion of glioma cells to WT are representative of the changes seen at the other affected super-enhancer-linked genes." (PMID 32647372, 2020). "In our study, ectopic expression of ASCL1 in human glioma cells instructed them reprogramming into a hybrid of neurons, including glutamatergic and GABAergic interneurons." (PMID 31212628, 2019). "At 14 dpi, when a majority of glioma cells had been reprogrammed into neurons by ASCL1, immunocytochemical analysis showed that 81.4% of glioma cells were positive for Ki67 in the control group, whereas only 23.1% of them were Ki67-positive in the ASCL1 group." (PMID 31212628, 2019). "By screening, we here found that ASCL1 or NGN2 alone is sufficient to convert human glioma cells into neuron-like cells." (PMID 31212628, 2019). "Of note, data analysis of gene expression and survival curves of 676 glioma samples obtained from TCGA showed that the patients with high expression of transcription factor ASCL1 and neuronal markers had a better survival." (PMID 31212628, 2019). "After infection glioma cells with ASCL1-expressing virus, however, their growth reached a plateau at seven dpi and no significant expansion was detected thereafter." (PMID 31212628, 2019). "Lastly, prior studies have suggested that NG2‐glia represent a potential cell of origin for some gliomas, such as glioblastoma multiforme, an aggressive, treatment‐resistant brain tumor characterized by high ASCL1 expression." (PMID 29683222, 2018). "OLIG2 is required for proliferation of multipotent neural progenitors and for glioma formation in a mouse model of gliomagenesis and it is also expressed in replicating oligodendrocyte precursor cells where it cooperates with ASCL1 to specify oligodendrocytes." (PMID 29759978, 2018). "ASCL1 expression is maintained in NSCs and glioma stem cells in culture, where it is essential for their proliferation and self-renewal in part through activation of Wnt signalling." (PMID 29759978, 2018). "Glioma stem cells derived from individuals with high ASCL1 expression remained more competent to undergo terminal neuronal differentiation in response to Notch inhibition compared with glioma stem cells expressing low ASCL1." (PMID 29759978, 2018). "As well as a high level of expression in NBs, ASCL1 levels were also elevated in other neural-based tumours (glioma and ependymoma), whereas other tumour types showed lower levels." (PMID 25786414, 2015). "In a recently developed mouse model of gliomagenesis, high RAS/ERK levels were found to modify Ascl1 activity giving rise to glial tumors, and we observe clear up-regulation of ASCL1 in the pilocytic astrocytomas." (PMID 26682910, 2015).
glioma (continued). "Here, we describe the efficient generation of induced neuronal (iN) cells from glioma cells by the infection with three transcription factors: Ascl1, Brn2 and Ngn2 (ABN)." (PMID 22859994, 2012). "Only Ascl1 acting as single transcription factor resulted in conversion of a few glioma cells to glioma cells to neurons, however the efficiency is low (less than 1%)." (PMID 22859994, 2012). "In gliomas, ASCL1 activates neuronal differentiation pathways and suppresses tumorigenicity." (PMID 39874041, 2025). "Finally, glioma initiation and formation were completely compromised in the majority of Ascl1;Olig2-dCKO mice, highlighting the redundant function of ASCL1 and OLIG2 as prominent transcription factors hijacked by tumor-initiating events." (PMID 39609428, 2024). "A similar result was found via overexpression of NGN2, ASCL1, and NeuroD1 in glioma cells." (PMID 36229714, 2023). "Gliomas and medulloblastomas are the most common types of brain tumors; several studies reported that the aberration of Notch components in brain tumors, for example, the overexpression of Notch1, 3 and 4, ASCL1, and Hey1, are highly correlated with a higher grade of glioma and poor prognosis." (PMID 38201528, 2023). "Importantly, the earliest detectable glioma cells in those models expressed the same molecular markers (Ascl1/Olig2) that we detected in AD-tdTomato+-NSCLs." (PMID 36841240, 2023). "Second, Ascl1 and Neurog2 triggered distinct transcriptional changes in human glioma cells, which may have explained different neuronal fates after conversion." (PMID 33755378, 2021). "In addition, glioma cell lines overexpressing ASCL1 can drive efficient conversion of these glial derivatives into neurons if induced to differentiate." (PMID 34012965, 2021). "The elevated ASCL1 in mutant H3.3 glioma may be accompanied by selective inhibition of its differentiation-promoting, pro-neural function." (PMID 32647372, 2020). "In contrast, in vivo we found that Ascl1;Nf1;Tp53CKO mice (hence forth referred to as Ascl1CKO tumor mice, N = 39) still developed high‐grade tumors that were phenotypically consistent with high‐grade gliomas." (PMID 32573857, 2020). "Accordingly, ASCL1 knockdown or conditional gene knockout prolong survival of glioma-bearing mice." (PMID 33076453, 2020). "To test whether ASCL1 is acting downstream of K27M, we performed small interfering RNA (siRNA) knockdown of ASCL1 in our parental and gene-edited glioma lines." (PMID 32647372, 2020). "Despite these findings, RNA‐seq from a Nf1;Tp53CKO mouse model of glioma where the tumors also lack ASCL1 revealed that although some Notch related genes (Dll3, Hes5, Hes6) were decreased, expression of many of the Wnt related genes seemed unaffected by the loss of ASCL1." (PMID 32573857, 2020). "Currently, the direct requirement of ASCL1 in brain tumor formation and progression from low‐grade gliomas to high‐grade GBMs in vivo remains unknown." (PMID 32573857, 2020). "Indirect evidence that NOTCH signaling could have tumor suppressor activity in glioma comes from studies on the proneural transcription factor ASCL1, whose expression is normally repressed by canonical NOTCH targets of the HES/HEY family in NSCs and GSCs." (PMID 33076453, 2020). "Consistent with U251, the time-course immunocytochemical analysis with neuronal markers DCX, TUBB3 and MAP2, showed that ASCL1 alone could also rapidly and efficiently reprogram U87 human glioma cells into neuron-like cells." (PMID 31212628, 2019). "We next performed orthotopic cell transplantation experiments to determine whether the ASCL1-mediated neuronal reprogramming could inhibit the tumorigenic potential of human glioma cells in vivo." (PMID 31212628, 2019). "Because neuron is a population of postmitotic cells, we further determined whether the aggressive proliferation of glioma cells could be inhibited by the ASCL1-mediated neuronal reprogramming." (PMID 31212628, 2019).
glioma (continued). "Recent study has showed that cultured human glioma cells could be converted into neuron-like cells by overexpression of three neurogenic transcription factors ASCL1, BRN2 and NGN2 (Neurogenin-2)." (PMID 31212628, 2019). "At three weeks post transplantation, marked GFP-labeled tumor masses were readily detectable in the brains transplanted with the control GFP but not ASCL1-infected U251 cells (data not shown), suggestive of the reduced tumorigenic activity of ASCL1-expressing human glioma cells in vivo." (PMID 31212628, 2019). "Taken together, all these results suggested that the single transcription factor ASCL1 may be sufficient to reprogram glioma cells into neurons, representing a feasible strategy for human malignant glioma treatment." (PMID 31212628, 2019). "Importantly, ASCL1-mediated neuronal reprogramming drives human glioma cells to exit the cell cycle and results in dramatic inhibition of proliferation, both in vitro and in vivo." (PMID 31212628, 2019). "Although the transcription factor ASCL1 is required for GSCs to undergo neuronal lineage differentiation, it remains unknown whether ASCL1 can induce neuronal reprogramming of glioma cells." (PMID 31212628, 2019). "ASCL1 is frequently expressed in malignant brain tumours, including oliogdendroglioma, diffuse astrocytoma and proneural type glioblastoma, as well as in primary glioblastoma and lower grade gliomas." (PMID 29759978, 2018). "Jiao and colleagues have shown that iN cells could be effectively derived from glioma cells by a combination of Ascl1, Brn2 and Ngn2." (PMID 28832532, 2017). "Thus, the combination of three transcription factors Ascl1, Brn2 and Ngn2 indeed drove human glioma cells to become neurons from mitotic cells." (PMID 22859994, 2012). "Primary glioma cells, U251 or U87 cells were infected with Ascl1, Brn2 and Ngn2 lentiviral virus." (PMID 22859994, 2012). "In this study, we showed that a combination of three transcription factors Ascl1, Brn2 and Ngn2, could efficiently convert human glioma cells to functional neurons." (PMID 22859994, 2012). "Due to its ability to interact with ATP-dependent BAF SWI/SNF chromatin remodeling complex, ASCL1 also plays a role in the regulation of chromatin structure, primarily at its target promoters, in embryonic stem cells and neural progenitors, as well as in glioma cell lines." (PMID 37958729, 2023). "However, ASCL1 is also expressed in transit amplifying cells derived from adult subventricular neural stem cells, proliferative OPCs, dividing glioma cells and even neuroendocrine cells of endodermal tissues such as the lung, and is crucially involved in small lung cancer formation." (PMID 35748297, 2022). "All these findings indicated that the single transcription factor ASCL1 could also reprogram human glioma cells into terminally differentiated neurons in vivo, which contributed to blocking the aggressive proliferation of human glioma cells and inhibiting their tumorigenicity in the brain." (PMID 31212628, 2019). "Similar to during gliogenesis, the levels and functional interactions of ASCL1 and OLIG2 then determine the cell types and degree of migration of glioma tumors that are generated." (PMID 39609428, 2024). "Similar to control tumors, Ascl1-OE GFP+ tumor cells co-localized with either GFAP or SOX10, indicating a “mixed glioma” phenotype." (PMID 39609428, 2024). "Overexpression of three neurogenic transcription factors (ASCL1, BRN2, and NGN2) reprogrammed 20%–40% of human glioma cells into TUBB3-positive neurons in vitro." (PMID 36229714, 2023). "Therefore, ASCL1's function in gliomas likely depends on its expression levels and on the presence of other factors that modulate its activity, and could contribute to locking cells into a state characterized by properties of both neuronal and glial progenitors." (PMID 32142668, 2020).
glioma (continued). "Overall, our findings illustrate that ASCL1, OLIG2, and SOX2 are coexpressed in tumor cells of both early and terminal tumors of the glioma mouse model in vivo, and tumor cells maintain a molecular identity reminiscent of that of OPCs." (PMID 32573857, 2020). "However, ASCL1 could rapidly and efficiently reprogram human glioma cells into neuron-like cells." (PMID 31212628, 2019). "Key genes involved in glioma cell differentiation, including ASCL1 and PTPRZ1-MET, have been shown to contribute to the development of a glioma stem cell phenotype, which is thought to be the source of resistance and relapse after initial treatment with checkpoint inhibitors." (PMID 38449858, 2024). "In contrast, we find that ASCL1 is not required for glioma formation in the brain of the mouse model, although disease progression is altered and the animals have extended survival." (PMID 32573857, 2020). "We here show that human glioma cells can be directly, rapidly and efficiently reprogrammed into terminally differentiated neuron-like cells by the single transcription factor ASCL1 (Achaete-scute complex-like 1, also known as MASH1)." (PMID 31212628, 2019). "It has been proposed that glioma CSCs express differentiation markers similar to those in normal glia and neurons, such as of oligodendrocytes (ASCL1, OLIG2 and DLL3), astrocytes (GFAP), neurons (β-tubulin III, SYT1 and SLC12A5), and markers of inflamed astroglial cells (SERPINE1, TGFB1 and RELB)." (PMID 31661894, 2019). "In the present study, we screened a series of transcription factors and found that ASCL1 alone could rapidly, efficiently and directly reprogram human glioma cells into non-proliferating neurons." (PMID 31212628, 2019). "In summary, this proof-of-concept study indicated that the single transcription factor ASCL1 was sufficient to high-efficiently reprogram human glioma cells into non-proliferating neurons and restricted tumor growth, suggestive of a promising potential for brain tumor treatment." (PMID 31212628, 2019). "Here, we showed that ASCL1 alone could rapidly, efficiently, and directly reprogram human glioma cells into non-proliferating neurons, resulting in significant inhibition of tumor growth." (PMID 31212628, 2019). "Finally, ASCL1 was shown to interact with both WNT and NOTCH signaling pathways to control neuronal differentiation and the tumorigenicity of glioma cell lines, genetically engineered glioma mouse models, and brain tumors of patient-derived xenograft (PDX)-GBM." (PMID 37958729, 2023). "Furthermore, analysis of gene expression and survival curves was performed on the data of 676 glioma samples obtained from The Cancer Genome Atlas (TCGA), showing that the patients with high expression of transcription factor ASCL1 but not NGN2 had a better survival." (PMID 31212628, 2019). "Both vGluT1 and GABA -positive neurons could be observed in the ASCL1-mediated glioma cell-to-neuron system, while no ChAT signal was detected in the culture, suggesting that ASCL1 reprogrammed glioma cells into inhibitory/excitatory interneurons but not motor neurons." (PMID 31212628, 2019). "Thus, although ASCL1 binds to and may contribute to the regulation of some of these target genes, particularly in an in vitro setting, expression of many of these target genes remains in gliomas in vivo in the absence of ASCL1." (PMID 32573857, 2020). "Of note, only 18.8% of the ASCL1-expressing (GFP+) cells were labeled by Ki67, while 81.2% of the Ki67-positive cells were detected in the non-infected (GFP-) glioma cells." (PMID 31212628, 2019).
neuroblastoma (37 papers, 2004 to 2025). Neuroblastoma (NB) is the most common solid, extracranial childhood tumor. "To search for possible spatial interactions of the ASCL1 promoter with SZ-associated loci, we used the neuroblastoma cell line SH-SY5Y." (PMID 37958729, 2023). "Higher levels of ASCL1 are associated with poorer neuroblastoma disease outcomes, and ASCL1 expression in neuroblastoma is negatively correlated with expression of genes involved in terminal neuronal differentiation." (PMID 36263020, 2022). "We find that deletion of ASCL1 results in downregulation of genes associated with more mature neuronal function in neuroblastoma cells." (PMID 36263020, 2022). "Consistent with a role for ASCL1 in supporting a neural identity in neuroblastoma cells, genes downregulated on ASCL1 KO that were also associated with an ASCL1 binding peak in our previous ASCL1 over-expression analysis were also involved in neurogenesis." (PMID 36263020, 2022). "ASCL1 encodes a bHLH transcription factor that has previously been implicated in neuronal cell development and neuroblastoma pathogenesis." (PMID 31819055, 2019). "Thus, ASCL1 functions to maintain chromatin accessibility of genes associated with neuronal identity and function in neuroblastoma cell lines." (PMID 36263020, 2022). "Notably, analysis using the R2 database indicated that high ASCL1 expression was significantly associated with inferior survival of neuroblastoma patients in a cohort reported by Kocak et." (PMID 31819055, 2019). "Studies have shown that hnRNPR and hnRNPA2B1 bind to and stabilize ASCL1 mRNA in a m6A-dependent manner, thereby promoting the progression of neuroblastoma." (PMID 40344709, 2025). "Using human neuroblastoma cells as a model system, we show that ASCL1 exhibits cell cycle phase-dependent chromatin binding patterns." (PMID 40452575, 2025). "In neuroblastoma cells, knockout of ASCL1 reduces in vitro proliferation rate, while overexpression drives potent cell cycle exit and neuronal differentiation." (PMID 40452575, 2025). "Although ASCL1 is a well-established regulator in neuroblastoma and other cancers, its role in hematopoietic malignancies is still under investigation." (PMID 40707954, 2025). "In adrenergic neuroblastoma cells, ASCL1 is part of the CRC that maintains cell identity and controls cell proliferation." (PMID 40527452, 2025). "That ASCL1 promotes pro-mitotic gene expression and cell cycle progression is at odds with our previous studies showing that ASCL1 overexpression drives potent neuronal differentiation in neuroblastoma cells." (PMID 40452575, 2025). "TF binding analysis in cell types such as neural stem cells and neural-committed neuroblastoma cells indicate that ASCL1 binds predominantly at enhancer and intergenic regions, rather than promoters." (PMID 40527452, 2025). "Phosphorylation via cyclin-dependent kinases (CDKs) and other kinases can phosphorylate ASCL1 in both neuroblastoma and glioblastoma stem cells." (PMID 40527452, 2025). "ASCL1 has also emerged as an important player in cancers like neuroblastoma and glioblastoma, underscoring the clinical need for a robust understanding of how ASCL1 controls cell identity." (PMID 40527452, 2025). "In the GI-ME-N neuroblastoma cell line, ASCL1 overexpression led to increased H3K27ac signals around the CRBN promoter region, suggesting transcriptional activation." (PMID 40551250, 2025). "We have previously shown that ASCL1 overexpression in neuroblastoma cell lines results in its widespread binding near loci associated with neuronal structures and functions, leading to subsequent neuronal differentiation." (PMID 40452575, 2025). "In other contexts (i.e. mammalian neuroblastomas), regulatory activity of ASCL1 has been shown to decrease in response to hypoxia." (PMID 38889788, 2024).